SIRPA (signal regulatory protein alpha)
Diseases named in the same sentence as SIRPA in open-access papers (continued):
Sharing a sentence is not in itself a finding about the gene and the disease.
inflammatory bowel disease (4 papers, 2012 to 2024). A spectrum of small and large bowel inflammatory diseases of unknown etiology. "SIRPα agonists have demonstrated efficacy in controlling inflammation by suppressing myeloid cell activity in patients with inflammatory bowel disease." (PMID 39160226, 2024). "In mice, studies have demonstrated that the SIRPα+CD103− APC subset may be involved in the generation of inflammatory bowel disease, inducing a Th17 response both in vitro and in vivo." (PMID 22442714, 2012). "Additionally, we examined the expression of Sirpα and Cd47 in immune cells, including ILC2s, within the intestinal tract and abdominal cavity of a mouse model of inflammatory bowel disease using public databases, and the results were comparable to the mouse asthma model." (PMID 39160226, 2024).
metastatic melanoma (4 papers, 2022 to 2025). A melanoma that has spread from its primary site to another anatomic site. "This work was undertaken following the finding that PMN-MDSCs devoid of SIRPα in patients with metastatic melanoma demonstrated a strong capacity to kill T cells using trogocytosis and production of ROS, without in vitro activation." (PMID 35795660, 2022). "Hence, antibody-engineered marrow macrophages/monocytes in marrow with SIRPα-blockade and clinically relevant anti-Tyrp1 can in principle out-compete and thereby repress human metastatic melanoma." (PMID 35454837, 2022). "Given that high expression of checkpoints PD-1, PD-L1, VISTA, SIRPα, and CD47 expression associated with anti-PD-1 response in our cohort, it remains to be investigated whether combination therapy with myeloid checkpoint blockade can overcome anti-PD-1 resistance in metastatic melanoma." (PMID 40897819, 2025).
oral squamous cell carcinoma (4 papers, 2016 to 2024). "The expression of SIRPα in oral leukoplakia (OLK) and oral squamous cell carcinoma (OSCC), and further explored the role of SIRPα on the phenotype, phagocytosis ability, migration, and invasion of macrophages in OSCC were investigated." (PMID 27793032, 2016).
prostate carcinoma (4 papers, 2019 to 2025). A carcinoma that arises from epithelial cells of the prostate gland. "CRD domain of SP-D is known to interact with CD14, TLR-2, TLR-4, EGFR, and SIRPα that are reported to be present on prostate cancer cells and normal prostate tissues." (PMID 31355132, 2019). "Thus, targeting CXCR2 could not only reverse CD47/SIRPα-mediated resistance to phagocytosis and suppress M2 macrophage polarization but also counteract NED in prostate cancer cells." (PMID 41163221, 2025).
renal carcinoma (4 papers, 2018 to 2023). A carcinoma arising from the epithelium of the renal parenchyma or the renal pelvis. "A bsAb combining the variable domain of the CD70 antibody vorsetuzumab with the variable domain of SIRPα‐targeting antibody KWAR23 induced more macrophage‐mediated phagocytosis in four out of four renal carcinoma cell lines compared to treatment with SIRPα‐Fc." (PMID 35908284, 2022). "Depletion of NK cells similarly attenuated the anti-tumor activity of a SIRPα blocking antibody in a syngeneic murine renal carcinoma model, but the same antibody did not inhibit NK killing of the tumor cells in vitro, further supporting a SIRPα-independent function of CD47 in NK cells." (PMID 30643501, 2018).
sarcoma (4 papers, 2021 to 2023). A usually aggressive malignant neoplasm of the soft tissue or bone. "The other TAM marker, SIRPA, was identified in macrophages in 31% of the sarcomas, especially chordoma (71% of the cases), dedifferentiated liposarcoma (77%), angiosarcoma (75%), and well-differentiated liposarcoma (65%)." (PMID 37958467, 2023). "This study is the first to investigate soluble forms of the macrophage markers SIRPα, LILRB1, CD163, and CD206 in sarcoma, and its conclusions are in accordance with a large study conducted by Dancsok showing that SIRPα in tissue samples is an adverse prognostic factor for soft tissue sarcomas." (PMID 36900335, 2023). "Furthermore, the appearance of SIRPα+ macrophages was also an adverse prognostic agent in both SS and myxofibrosarcoma, and it was associated with a worse OS in sarcomas without translocations." (PMID 37958467, 2023). "Furthermore, the expression of CD47 and SIRPA showed poor positive correlations with CD68+ and CD163+ macrophages in almost all sarcomas, except a solitary fibrous tumor, demonstrating a significant negative correlation between CD163+ and CD68+ TAMs, and CD47." (PMID 37958467, 2023).
acute lymphoblastic leukemia (3 papers, 2013 to 2023). Leukemia with an acute onset, characterized by the presence of lymphoblasts in the bone marrow and the peripheral blood. "While no expression was observed among acute lymphoblastic leukemia (ALL) cell lines, AML cell lines differentially expressed the SIRPα protein." (PMID 23320069, 2013).
autoimmune hemolytic anemia (3 papers, 2017 to 2024). Autoimmune hemolytic anemia (AIHA) is an autoimmune disorder in which various types of auto-antibodies are directed against red blood cells causing their survival to be shortened and resulting in hemolytic anemia. "Owing to highly expressed CD47 on normal red blood cells, disruption of CD47/SIRPα axis may result in lethal autoimmune hemolytic anemia." (PMID 39429877, 2024).
cardiac hypertrophy (3 papers, 2015 to 2022). "A role for SIRPA in cardiac diseases is not fully established except for one study showing a protective role of SIRPA in cardiac hypertrophy through negative regulation of the Toll-like receptor 4/nuclear factor-kB pathway in vitro." (PMID 27474398, 2016).
chordoma (3 papers, 2022 to 2023). Chordomas are rare malignant tumors arising from embryonic remnants of the notochord in axial skeleton. "Furthermore, CD47 was correlated with SIRPα score, with the highest expression observed in chordoma, angiosarcoma, and pleomorphic liposarcoma." (PMID 36900335, 2023). "The effects of many immune checkpoints, including LAG3, TIM3, SIRPα, HHLA2, MAGEA4, VISTA and TIGIT, have been validated in chordoma, and five of them (TIM3, SIRPα, HHLA2, MAGEA4 and VISTA) were only evaluated in preclinical study." (PMID 36612259, 2022). "A variety of immunosuppressive checkpoints such as PD-1/PD-L1, CD47/SIRPα, TIM3, and CTLA4 are expressed on the surface of both chordoma cells and immune cells, and ICIs are the most widely performed strategy in the field of chordoma immunotherapy." (PMID 37720221, 2023). "CD47, SIRPα, and TIM3 are all expressed on TAMs, and chordoma CD47 expression shows the highest degree of expression among various sarcomas, However, whether it can be used as a prognostic factor and therapeutic target for chordoma is currently unknown." (PMID 37720221, 2023).
esophageal squamous cell carcinoma (3 papers, 2022 to 2026). Esophageal squamous cell carcinoma (ESCC) is a type of esophageal carcinoma (EC) that can affect any part of the esophagus, but is usually located in the upper or middle third. "SIRPα is also expressed on TAMs, and recent evidence links high SIRPα expression to poor survival in patients with esophageal squamous cell carcinoma." (PMID 35883493, 2022). "The single cell RNA sequencing data of myeloid cells integrated from several cancers including esophageal squamous cell carcinoma was analyzed for characterizing the function and cellular interactions of SPP1 + macrophages expressing SIRPα." (PMID 39696410, 2024).
gastric cancer (3 papers, 2021 to 2024). A primary or metastatic malignant neoplasm involving the stomach. "The utilization of SIRPα-Fc in anti-CD47 therapy has demonstrated remarkable efficacy in Hu-PDX models of gastric cancer." (PMID 38532108, 2024). "Consequently, we established a post-surgical gastric cancer model to assess the efficacy of SIRPα-VEGFR1 in preventing recurrence." (PMID 38532108, 2024). "Before examining the impact of targeting the CD47/SIRPα axis, we utilized CD47+ gastric cancer patient-derived cells (PDC1 and PDC2) and verified their identity through flow cytometry analysis." (PMID 38532108, 2024). "Our study has shown that CD47 serves as a viable therapeutic target for gastric cancer, and it has also presented a potentially effective combination approach involving the inhibition of both the CD47/SIRPα axis and angiogenesis for the treatment of this disease." (PMID 38532108, 2024). "Furthermore, SIRPα-VEGFR1 demonstrated a sustained immune response, effectively preventing the recurrence of gastric cancer and extending overall survival in a recurrence model." (PMID 38532108, 2024).
hematoma (3 papers, 2022 to 2025). A hematoma is a collection of blood from a vascular structure into an extravascular space. "This study describes a nanoregulator formed through the self‐assembly of Mg2+ and signal regulatory protein α (SIRPα) DNAzyme (SDz), aimed at enhancing hematoma resolution and inhibiting neuroinflammation in the treatment of ICH." (PMID 39520083, 2025). "In this study, a nanoregulator (SDz) is introduced, formed through the self‐assembly of Mg2+ and SIRPα DNAzyme, to improve hematoma resolution and suppress neuroinflammation following ICH." (PMID 39520083, 2025). "Compared with the Con group, SIRPα-v Exos accelerated hematoma clearance and ameliorated motor and cognitive decline and depressive-like behaviors." (PMID 36435797, 2022). "Collectively, our findings revealed that SIRPα-v Exos accelerated the clearance of hematoma and alleviated WMI by regulating the polarization of microglia/macrophages." (PMID 36435797, 2022). "We show that modified exosomal SIRPα variants block the CD47-SIRPα interaction and promote hematoma clearance, relieving WMI after ICH." (PMID 36435797, 2022). "Furthermore, strategies that inhibit SIRPα on microglia and macrophagesoffer an alternative approach to promote hematoma clearance." (PMID 41504200, 2025). "Our studies revealed that SIRPα-v Exos could accelerate the clearance of hematoma and ameliorate secondary white matter injury after ICH through regulation of microglia/macrophages." (PMID 36435797, 2022). "In addition, SIRPα-v Exos recruited regulatory T cells (Tregs) to promote M2 polarization of microglia/macrophages in the peri-hematoma tissue." (PMID 36435797, 2022).
Hyperglycemia (3 papers, 2009 to 2026). An increased concentration of glucose in the blood. "Finally, suppressing SIRPα in skeletal muscles or treatment with anti-SIRPα monoclonal antibodies in STZ-treated mice mitigated cachexia, hyperlipidemia, kidney triglyceride deposition, and renal dysfunction in spite of significant hyperglycemia." (PMID 41657313, 2026).
liver fibrosis (3 papers, 2023 to 2025). "A recent study suggested that SIRPα+ macrophages infiltration was elevated in nonalcoholic steatohepatitis (NASH), and anti-SIRPα promoted necroptotic hepatocytes engulfment and inhibited hepatic fibrosis." (PMID 40523887, 2025).
metastatic tumors (3 papers, 2015 to 2024). "As such, in addition to support the notion that proper engagement of CD47 and SIRPα is important for establishment of metastatic tumors, this study also suggests that PC3-mCD47 cells may represent a better metastatic model than PC-3 M-LN4 for preclinical investigations." (PMID 26674012, 2015).
pneumonia (3 papers, 2021 to 2024). An acute, acute and chronic, or chronic inflammation focally or diffusely affecting the lung parenchyma, caused by an infection in one or both of the lungs (by bacteria, viruses, fungi, or mycoplasma.). "Alveolar macrophages from patients recovered from primary pneumonia exhibited poor phagocytic capacity for several weeks in a SIRPα-dependent way, and blockade of SIRPα restored phagocytosis." (PMID 39737178, 2024). "This epigenetic reprogramming was induced by sustained secondary inflammatory mediator signaling and enhanced SIRPα expression and activity from the post-pneumonia lung environment, rather than bacterial pathogen products from primary pneumonia." (PMID 33572846, 2021).
Sepsis (3 papers, 2021 to 2025). Sepsis is defined as life-threatening organ dysfunction caused by a dysregulated host response to infection. "In an in vitro model of sepsis-related ARDS, co-culture with transgene-inactive and transgene-active HSD-1 tMSCs had no impact on AM surface expression of C206, CD163, CD80, SIRPα or Mer." (PMID 39036559, 2024).
triple-negative breast carcinoma (3 papers, 2013 to 2024). An invasive breast carcinoma which is negative for expression of estrogen receptor (ER), progesterone receptor (PR), and human epidermal growth factor receptor 2 (HER2). "Similarly, in humanized mice engrafted with human CD34+ cells from donors with v1/v2 SIRPA genotype bearing MDA-MB-231 triple negative breast cancer (TNBC) tumors, AB21 significantly decreased antitumor activity while clone HEF-LB had no impact on tumor growth." (PMID 33256806, 2020).
acute promyelocytic leukemia (2 papers, 2016 to 2025). An aggressive form of acute myeloid leukemia (AML), characterized by arrest of leukocyte differentiation at the promyelocyte stage, due to a specific chromosomal translocation t(15;17) in myeloid cells. "In the present study, we demonstrate that overexpression of SIRPα in acute promyelocytic leukemia (APL) cells results in apoptosis possibly via inhibiting the β-catenin signaling pathway and upregulating Foxo3a." (PMID 27010069, 2016). "Contrastingly, in acute promyelocytic leukemia (APL) cells, overexpression of SIRPα exhibits distinct effects, potentially inhibiting the β-catenin signaling pathway and upregulating Foxo3a expression, which in turn induces apoptosis and inhibits tumor cell proliferation." (PMID 40589735, 2025).
asthma (2 papers, 2024). "While this study had a limited sample size, and further investigation is warranted, these results suggest that SIRPα may serve as a promising therapeutic target for asthma management." (PMID 39160226, 2024). "Overall, these results suggest that targeting SIRPα on ILC2s may be a feasible approach for treating asthma." (PMID 39160226, 2024). "Targeting of SIRPα is therefore a potential new therapeutic approach to suppression of mucin hypersecretion in chronic airway diseases such as COPD and asthma." (PMID 38245585, 2024). "We analyzed the expression of Sirpα and Cd47 in Th1, Th2, Th17, ILC1, ILC2, and ILC3 cells using publicly available scRNAseq data generated from a mouse asthma model." (PMID 39160226, 2024). "Moreover, we evaluated the expression of SIRPα in peripheral blood ILC2 in both healthy subjects and individuals with asthma." (PMID 39160226, 2024). "Treatment targeting the SIRPα–SHP-1 axis, such as administration of exogenous recombinant SP-D, might therefore be expected to suppress mucin overproduction in individuals with COPD or asthma." (PMID 38245585, 2024). "Our experiments using genetically modified mice showed that the absence of either SIRPα or CD47 leads to increased ILC2 function, development AHR and lung inflammation in both acute and chronic models of asthma." (PMID 39160226, 2024).
brain cancer (2 papers, 2022 to 2025). A primary or metastatic malignant neoplasm affecting the brain. "SIRPA is also prevalent in healthy brain tissues; nevertheless, its high level in brain cancers suggests that the SIRPA-CD47 interaction may be highly important in gliomas across both species." (PMID 40788962, 2025).
breast tumor (2 papers, 2021 to 2025). "The adaptive immune checkpoints BTNL9 and VTCN1 and the innate immune checkpoints CD200 and SIRPA were downregulated in breast tumor tissues while the metabolic immune checkpoints ADORA2A and TDO2 were upregulated in breast tumor tissues." (PMID 33932112, 2021).
chondrosarcoma (2 papers, 2022 to 2023). A malignant cartilaginous matrix-producing mesenchymal neoplasm arising from the bone and soft tissue. "SIRPA+ TAMs were observed in both conventional and dedifferentiated chondrosarcoma." (PMID 37958467, 2023). "Similarly, SIRPA+ and CSF1R+ TAMs were related to the metastatic status at diagnosis and a poor OS in patients with dedifferentiated chondrosarcoma." (PMID 37958467, 2023). "In this study, increased expressions of lymphocyte activation gene-3 (LAG3), T cell immunoglobulin mucin (TIM3), B7 superfamily member-H3 (B7H3), signal regulatory protein alpha (SIRPA), and colony-stimulating factor 1 receptor (CSF1R) were observed in chondrosarcoma." (PMID 35163019, 2022).
colorectal adenocarcinoma (2 papers, 2020 to 2025). The most common type of colorectal carcinoma. "We calibrate the model using tumor growth data from a preclinical study using treatment-resistant colorectal adenocarcinoma (MC38) in WT (C57BL/6) and SIRPα−/− mice, with and without local irradiation." (PMID 41296731, 2025).
depression (2 papers, 2021 to 2022). "This Src/Fyn-SIRPα-Shp2 pathway seems to be mobilized to reduce depression risk since mutant mice lacking most of the tyrosine-phosphorylated cytoplasmic region of SIRPα or lacking the SIRPα ligand CD47 manifested the increased immobility time relative to wild-type (WT) mice." (PMID 35164461, 2022).
diabetic kidney disease (2 papers, 2024 to 2026). Progressive kidney disorder caused by vascular damage to the glomerular capillaries, in patients with diabetes mellitus. "Looking at the expression levels of these proteins in patients suffering from diabetic nephropathy (DN), we found a down-regulation of the expression (log2 fold change: SIRPA: -0.902; IQGAP2: -0.578)." (PMID 38605154, 2024).
malaria (2 papers, 2022 to 2025). Malaria is a serious and sometimes fatal disease caused by a parasite that commonly infects a certain type of mosquito which feeds on humans. "Overall, the interaction between CD47 on RBCs and SIRPα on macrophages is crucial in regulating erythrophagocytosis in malaria." (PMID 41171200, 2025). "Nevertheless, further studies are still required to better understand the role of SIRPα modulation in malaria immunity and pathogenesis." (PMID 35630348, 2022). "The present study attempted to investigate if malaria parasites are endowed with the capacity of modulating the expression of SIRPα on cells of innate immune system." (PMID 35630348, 2022). "To gain insight into SIRPα in malaria, in the present work, we investigate the modulatory effect of Plasmodium crude extracts on SIRPα expression in peripheral blood innate immune cells." (PMID 35630348, 2022). "Notwithstanding, little attention has been given to SIRPα in the context of immunosuppressive states induced by malaria." (PMID 35630348, 2022). "We hypothesize that malaria parasites explore inhibitory signaling of SIRPα to suppress antiparasitic immune responses contributing to the establishment of infection." (PMID 35630348, 2022).
myeloid malignancies (2 papers, 2021 to 2022). "CD47/SIRPα axis-targeting agents are promising additions to the current therapeutic armamentarium in myeloid malignancies." (PMID 35883692, 2022). "In addition to the T-cell immune checkpoints, CD47 is the dominant MΦ checkpoint, which is overexpressed in myeloid malignancies and inhibits phagocytosis through “do not eat me” signals upon its binding to SIRPα on MΦs." (PMID 34771453, 2021).
myocardial infarction (2 papers, 2024). Gross necrosis of the myocardium, as a result of interruption of the blood supply to the area, as in coronary thrombosis. "Herein, a biomimetic nano‐degrader is developed to inhibit CD47‐SIRPα axis in a site‐specific manner through SIRPα degradation, and its efficacy in acute myocardial infarction (AMI) is evaluated." (PMID 38477522, 2024). "In this study, we introduced a biomimetic liposome as a nano‐degrader to degrade SIRPα on macrophage membrane and tested the effect on inhibition of CD47‐SIRPα immune checkpoint in myocardial infarction as the disease model." (PMID 38477522, 2024). "LPS and IL-4 function in a concerted way to alleviate mouse myocardial infarction by mediating Sirpα." (PMID 39707436, 2024).